FAT1 (FAT atypical cadherin 1)
Diseases named in the same sentence as FAT1 in open-access papers (continued):
Sharing a sentence is not in itself a finding about the gene and the disease.
tumor (continued). "In order to investigate a possible role of FAT1 in tumor-associated immunosuppression, we checked for any correlation between the expression of FAT1 in tumors and levels of immune cell infiltration using TIMER2.0." (PMID 35720420, 2022). "FAT1 encodes a tumor suppressor-related member of the FAT protocadherin family that is frequently mutated in numerous types of human cancers including cutaneous, head and neck, and oral SCCs." (PMID 35408839, 2022). "The mutation survival analysis of the top four tumors with more than 15% mutation rate demonstrated that FAT1 mutations in UCEC predicted better prognosis for tumor patients, but FAT1 mutations in HNSC predicted poor survival." (PMID 36517565, 2022). "Both oncogenic and tumor-suppressive roles of FAT1 are implicated in different cancers and have been attributed to tissue specificity or context specificity." (PMID 35720420, 2022). "The contributions of FAT1 mutations to tumor and the tumor microenvironment interaction, particularly to the immune regulatory system, have not been clarified." (PMID 35965328, 2022). "The positive FAT1 staining which resulted for these parameters was associated with age, differentiation, metastasis, and tumor budding, indicating that FAT1 has potential for clinical pathologic diagnosis." (PMID 35646625, 2022). "Further, we showed that presence of hypoxia in the tumor microenvironment, which is a hallmark of glioblastoma, upregulates FAT1 expression." (PMID 33878524, 2021). "The tumor with KRAS K117N also carried a FAT1 mutation present at the subclonal level in the primary tumor and later found to be enriched at time of relapse." (PMID 33384420, 2020). "While frequently encountered, the molecular mechanisms that contribute to tumor development in the context of FAT1 functional loss are poorly understood in cSCC." (PMID 32674318, 2020). "Fat1 was mutated in 30% of the tumours, particularly in moderate and severe dysplasias and invasive SCC." (PMID 33168804, 2020). "One study that focused on primary cSCCs from immunosuppressed and immunocompetent patients found FAT1 to be mutated in 60% of the tumor samples." (PMID 32674318, 2020). "We also mapped our data with top 20 mutated genes in CRC from COSMIC data sets and found FAT1 and FAT4 to be mutated in tumour, whereas distal margin showed the presence of FAT1, KRAS and SMAD4 mutations." (PMID 30950180, 2019). "Despite these facts, the molecular mechanisms that contribute to tumor development in the context of loss of FAT1 function are poorly understood." (PMID 31817001, 2019). "FAT1 was originally reported as a tumor suppression marker linked to E-cadherin and Wnt/β catenin pathways." (PMID 30416985, 2018). "We stratified tumor cases containing FAT1 and FAT2 alterations, including mutations, copy loss alterations or loss of expression (n = 188) and compared them to those exhibiting unaltered FAT1 and FAT2 (n = 76)." (PMID 29985391, 2018). "Genomic analysis has identified that FAT1 is a tumor suppressor and mutation of FAT1 leads to human cancer." (PMID 29228735, 2017). "FAT1 (NM_005245) encodes a tumor suppressor essential for controlling cell proliferation during Drosophila development." (PMID 27036947, 2016). "That group’s data showed two tumours with protein-truncating FAT1 mutations and a further cancer with a missense change, p.Ile2276Met, predicted to have severe functional effects (SIFT=0.05, Polyphen2=0.87)." (PMID 24777035, 2014).
tumor (continued). "To investigate whether FAT1 loss impacts YAP/TAZ protein degradation in tumor cells, we examined YAP and TAZ levels by treatment of protein synthesis inhibitor cycloheximide." (PMID 40478800, 2025). "Furthermore, immunofluorescence was also used to compare FAT1 expression in tumor-associated versus normal lymphatic vessels." (PMID 41230499, 2025). "Our previous findings indicated that the FAT1 mutation risk signature harbored strong correlations with tumor immunogenicity and related features, thus we hypothesize that this risk signature might play a role in evaluating the efficacy of immune therapy." (PMID 40672387, 2025). "In addition, high tumor mutation burden (TMB) associated with FAT1 mutations correlated with poor OS in HPV‐ HNSCC patients in TCGA cohort." (PMID 40407216, 2025). "A recent study conducted in mouse models of skin squamous cell carcinoma and lung cancer revealed that loss of FAT1 could accelerate tumor occurrence and malignant progression, promoting epithelial to mesenchymal transition (EMT)." (PMID 40672387, 2025). "However, our focus was confined to the role of FAT1 in the malignant attributes of tumor cells, omitting an investigation into the underlying causes of FAT1 mutation and its contribution to the transformation of normal cells into malignant tumor cells." (PMID 39781458, 2025). "Collectively, our results suggest that matrix mechanotransduction may serve as a key regulatory mechanism modulating tumor-associated lymphatic function through the regulation of FAT1 expression." (PMID 41230499, 2025). "However, through which mechanisms mutations of FAT1 lead to tumor progression is incompletely understood." (PMID 40478800, 2025). "FAT1 was prioritized as a top candidate of clinical relevance, as inactivating mutations in FAT1 were highly recurrent (~10%) in the TRACERx 421 cohort (comprising 421 patients and 1,644 tumour regions), with a notable proportion of FAT1 mutations occurring early before WGD." (PMID 39738653, 2024). "Consistent with a general role of FAT1 in the negative regulation of endothelial YAP/TAZ, we found that loss of FAT1 resulting in YAP/TAZ activation increased endothelial cell proliferation during postnatal retinal angiogenesis as well as in tumor angiogenesis." (PMID 37031213, 2023). "We then studied the effect of endothelial FAT1 deficiency on tumor angiogenesis." (PMID 37031213, 2023). "The aberrant dysfunction of FAT1 is primarily associated with tumor formation and growth." (PMID 37511534, 2023). "In addition to developmental and tumor angiogenesis, we found that loss of FAT1 also affected post-ischemia neovascularization." (PMID 37031213, 2023). "Chen and colleagues performed a literature review on the diverse functions of FAT1 in cancer progression and presented the phenotypic alterations due to FAT1 mutations, several signaling pathways and tumor immune systems known or proposed to be regulated by this protein." (PMID 36900131, 2023). "The FAT1 gene, located on chromosome 4q35, is the human ortholog of the Drosophila gene, ‘Fat’, and encodes the human atypical FAT1 transmembrane protein, which acts as a tumor suppressor." (PMID 35625959, 2022). "They demonstrated that FAT1 might reduce the tumor-initiating ability in NSCLCs by promoting Yes-associated protein 1 (YAP1) nuclear-cytoplasmic translocation." (PMID 35965328, 2022). "Recently, FAT1 mutations were identified in human cancers and may contribute to Wnt activation, suggesting that FAT1 may serve as a tumor suppressor in human cells." (PMID 35573184, 2022). "In addition to phenotypic alterations due to FAT1 mutations, several signaling pathways and tumor immune systems known or proposed to be regulated by this protein are presented." (PMID 35965328, 2022). "Loss of function of FAT1 contributed to tumor progression and impacted clinical outcomes." (PMID 35739249, 2022).
tumor (continued). "Another study on NSCLC was consistent with their observation and further suggested that high FAT1 mutation rate is associated with high tumor mutation burden (TMB), which could be used to predict patient response to ICIs." (PMID 35965328, 2022). "Because FAT1 functions as a tumor suppressor or promoter, depending on the variety of cancer, FAT1 alteration data need to be analyzed comprehensively, while considering the association between FAT1 and other genes." (PMID 34939311, 2022). "Then, combined with mechanistic studies, it jointly revealed that loss of function of FAT1 could activate a CAMK2-CD44-SRC axis to promote tumor initiation, progression, invasiveness, stemness, and metastasis." (PMID 36338621, 2022). "Additionally, we analyzed the association of FAT1 with tumors from multiple perspectives, including single-cell sequencing, mutations, high tumor mutational burden, microsatellite instability, immune cell infiltration, and immune microenvironment." (PMID 36517565, 2022). "The mutation frequencies of several tumor-suppressor genes including FAT1, CDKN2A, FGFR3, and CASP8 were lower in the HPV-positive group of HNSC, and even the mutation frequencies of FAT1, CDKN2A, and CASP8 were 0, indicating that the biological processes regulated by these genes were not disrupted." (PMID 35392231, 2022). "Inactivating FAT1 mutations, primarily in the form of homozygous deletions, but also in the form of protein-truncating nonsense mutations, strongly suggest that FAT1 functions as a tumor suppressor." (PMID 35456049, 2022). "Our data also implicated that FAT1 might function as the tumor suppression through the promotion of the expression of PTPN14 and inhibition of the expressions of Yap1 and Myc." (PMID 34712552, 2021). "Our results support the hypothesis that mutations in FAT1 negatively affect tumor progression in HPV−OPSCC patients." (PMID 33527763, 2021). "Consequently, our methods predict substantially fewer unseen variants in KRAS than in FAT1, while the corresponding estimate of the probability of observing at least one new variant in a new tumor is noticeably higher for FAT1 as compared to KRAS." (PMID 31796730, 2019). "This rationalization based on tumor heterogeneity and mutational status are therapeutically relevant as they go beyond the initial biological function ascribed to FAT1, and can inform discovery or development of novel anti-OSCC therapeutic strategies with high efficacy." (PMID 31783581, 2019). "However, in the patient 14 relapse tumor, there were two mutations in FAT1 in the PDX and a tumor-specific FAT1 mutation." (PMID 30134176, 2018). "At the initial stage of tumorigenesis, these mutated genes might be tumor-initiating SNVs in conjunction with the CNAs of FAT1, MYC, PARP10, and CYC1." (PMID 30143682, 2018). "How the respective FAT1 mutations identified in these individuals might contribute to neoplastic disease will require further focused study." (PMID 26905694, 2016). "Moreover, FAT1 mutations were also found to be closely associated with immunotherapy and may develop into tumor immunotherapy markers." (PMID 36517565, 2022). "However, as a relatively new gene implicated in cancer, it remains to be explored how FAT1 aberrations might contribute to various hallmarks of cancer leading to tumor development and progression." (PMID 35720420, 2022). "Thus, while the study identifies GPC3 as a binding partner of FAT1 and presents GPC3-FAT1 as a functional complex, it opens new avenues to study underlying mechanisms that may connect FAT1 with tumor-related signaling pathways." (PMID 33878524, 2021).
tumor (continued). "FAT1 suppression activates the Wnt/β-catenin pathway, positioning FAT1 as a potential tumor suppressor and offering a novel therapeutic target for BC treatment." (PMID 41362743, 2026). "Functionally, FAT1-KD significantly accelerated cell proliferation, supporting its role as a tumor suppressor." (PMID 41362743, 2026). "To further assess expression patterns, we analyzed FAT1 protein levels across 24 tumor types using the UALCAN database." (PMID 41362743, 2026). "This expression pattern was also reflected in FAT1 protein level differences between normal and tumor tissues." (PMID 40083689, 2025). "Intriguingly, even mLECs cultured on physiological soft matrices with FAT1 knockdown demonstrated FA numbers comparable to or exceeding those NC LECs on tumor-mimetic stiff matrices." (PMID 41230499, 2025). "Following failure of standard first line chemotherapy, high-throughput sequencing (HTS) revealed a high tumor mutational burden (TMB), pathogenic mutations in FAT1 and NOTCH2 and a microsatellite instability (MSI)-associated signature." (PMID 40248199, 2025). "In the present study, we revealed a previously unreported mechanism through which FAT1 exerts its tumor-suppressor effect by impeding the type I interferon pathway." (PMID 39781458, 2025). "Although its roles in tumor cells and vascular smooth muscle cells are established, FAT1 function in lymphatic endothelial cells remains largely unexplored." (PMID 41230499, 2025). "Loss of either FAT1 or MIB2 significantly elevates YAP/TAZ protein levels, enhances their transcriptional activity, and promotes tumor cell proliferation in both in vitro and in vivo models." (PMID 40478800, 2025). "Given that Notch can be either oncogenic or tumor-suppressive depending on the cellular context in various tumors including HNSCC, it is conceivable that loss of FAT1 affects Notch signaling in tumor cells through altered localization of MIB2." (PMID 40478800, 2025). "Here, we found that FAT1 knockdown markedly increased the stemness of tumor cells and increased their proliferative capacity." (PMID 39781458, 2025). "Most of these specific mutations (n = 20; 80%) were exclusive to NAT, including those affecting key genes such as NOTCH1 (the most mutated gene), FAT1, or PPARD; while 20% were shared between NAT and tumor tissue, affecting genes such as CDKN2A." (PMID 40465458, 2025). "We demonstrate that tumor-mimetic matrix stiffness significantly downregulates FAT1 expression, which likely contributing to enhanced proliferative and migratory capacities in LECs." (PMID 41230499, 2025). "The role of FAT1 in tumors has attracted increasing interest from researchers, with FAT1 being considered an emerging biomarker for tumor diseases and a target for new therapies or monitoring." (PMID 40242237, 2025). "Using the same manipulations as above, we extended our analysis to assess the contribution of FAT1 to TNBC tumor cell metastatic potential using wound healing and Transwell invasion assays." (PMID 40083689, 2025). "Further evaluation of the tumor by Caris Molecular Intelligence revealed several mutations, including the NF1 variant of uncertain significance (VUS), NRAS, PBRM1, FAT1, TERT Promoter, and ATM." (PMID 40125165, 2025). "This trend was similarly observed at the protein level, as Western blot results indicated significant upregulation of CXCL10, CXCL11, OAS2, MTIE, and MTIX in tumor tissues, although FAT1 exhibited an opposite trend compared to the qPCR results." (PMID 40574841, 2025).
tumor (continued). "Similar to Hela tumor cells with suppressed expression of FAT1 and MIB2, we also saw increased tumor growth in the HNSCC CAL27 with suppressed FAT1 and MIB2 expression after subcutaneous injection of cells into NOG mice." (PMID 40478800, 2025). "When analyzing the interactome of the cytoplasmic part of FAT1 in tumor cells, we identified the E3 ubiquitin ligase Mind Bomb-2 (MIB2) as an interaction partner." (PMID 40478800, 2025). "Overall, the inhibition of FAT1 promoted tumor growth in vivo, whereas the overexpression of STAT1/IRF9 inhibited the tumor-promoting effect induced by FAT1 knockdown." (PMID 39781458, 2025). "FAT1 acts as a tumor-suppressor gene, and loss of FAT1 function induces a hybrid epithelial-to-mesenchymal transition (EMT) phenotype that promotes tumor progression." (PMID 40478800, 2025). "This is supported by our in vivo data demonstrating that loss of FAT1 as well as of MIB2 increased YAP/TAZ protein levels and tumor growth of Hela cells as well as of HNSCCs and that FAT1-mediated reduction in tumor progression depended on MIB2." (PMID 40478800, 2025). "FAT atypical cadherin 1 (FAT1) is a well-known tumor regulator that plays a crucial role in multiple cancer signaling pathways." (PMID 40672387, 2025). "MDA-MB-231 cells bearing either the control shRNA or FAT1 shRNAs were cultured at low density in stem cell media before measuring the number and size of tumor spheres after 12 days." (PMID 40083689, 2025). "Studies have indicated that FAT1 can influence tumor cell proliferation, migration, invasion, stemness, and epithelial-mesenchymal transition (EMT) by regulating multiple signaling pathways, including Wnt/β-catenin, Hippo, and MAPK/ERK." (PMID 40242237, 2025). "In vivo gene depletion of mutant FAT1 with LNP‐sgFAT1 suppresses tumor growth and restores CPI‐613 sensitivity, revealing a targetable metabolic bypass with therapeutic potential in FAT1‐mutant cancer." (PMID 40407216, 2025). "RNA-seq identified robust induction of xenobiotic metabolism (CYP1A1, CYP1B1), oxidative/metabolic stress mediators (GDF15, TIPARP), and tumour-associated genes (FOSB, VGF), alongside repression of tumour suppressors (FAT1, LINC00472)." (PMID 41600570, 2025). "In this context, we reported that FAT1 was downregulated in tumor tissues/cells compared with normal tissues/cells and that it was correlated with the clinicopathological features and prognosis of HNSCC." (PMID 39781458, 2025). "In tumor cells, FAT1 interacts with the E3 ligase MIB2 to facilitate the ubiquitin-dependent degradation of YAP/TAZ." (PMID 40478800, 2025). "In prostate cancer models, FAT-1 expression inhibited tumour growth, increased apoptosis, and limited tumour cell invasion." (PMID 41002979, 2025). "FAT1, a gene with tumor suppressor functions in other cancers, was among the commonly mutated genes in our analysis." (PMID 41301029, 2025). "In a flank‐xenograft mouse model, a significant reduction in tumor volume and weight was observed in mice implanted with FAT1 KO cells compared to mice receiving parental cells." (PMID 40407216, 2025). "The present study demonstrates that MIB2-mediated YAP/TAZ degradation plays a crucial role in the tumor-suppressive function of FAT1." (PMID 40478800, 2025). "Depending on the tumor type, FAT1 has been shown to function as both an oncogene promoting HIF1α expression, invasiveness, and inflammation in advanced tumors, as well as a tumor suppressor by inhibiting Wnt signaling and tumorigenesis." (PMID 40458731, 2025). "While control Hela cells injected into NOG mice lead to tumor formation after 14 days, Hela cells with knock-down of FAT1 or MIB2 developed visible tumors as early as 9 days after injection." (PMID 40478800, 2025).